ICOS (inducible T cell costimulator)
Diseases named in the same sentence as ICOS in open-access papers (continued):
Sharing a sentence is not in itself a finding about the gene and the disease.
tumor (433 papers, 2011 to 2026). "In summary, tumor-released sICOSL induce the endocytosis and degradation of ICOS to cause T cells dysfunction." (PMID 40708008, 2025). "Using CellChat analysis, we demonstrated that tumor-associated dendritic cells, particularly plasmacytoid DCs, exhibit stronger ICOS-mediated communication with T cells compared to their counterparts in normal tissues." (PMID 41180156, 2025). "Increased proportions of ICOS+ T cells in peripheral blood and tumor microenvironment are associated with improved prognosis." (PMID 38506253, 2024). "Specifically, one HERV-H member (chr2:204826665-204832368) is located 365 bp from the ICOS (Inducible T-cell costimulatory) gene, which has been associated with tumor immune responses." (PMID 36774364, 2023). "Univariate analysis showed that the factors significantly associated with overall survival were tumor size, regional lymph node involvement, stage, and expression level of ICOS/ICOSL." (PMID 37850501, 2023). "Because clinical tumor staging includes tumor size and local lymph node condition, it can be concluded that both ICOS and ICOSL expressions are closely associated with stage status." (PMID 37850501, 2023). "A large body of evidence confirms that activation of the ICOS/ICOSL pathway is involved in the maintenance of T cells in the tumor microenvironment, which is usually associated with a poor prognosis of the patient." (PMID 37850501, 2023). "We examined the connections between ICOS and TMB, MSI, MMR genes, and DNMTs in order to further investigate the likely mechanism underlying the association between ICOS and tumor." (PMID 36855091, 2023). "Our results also indicate that a higher coexpression of CTLA-4, PD-L1, and ICOS in normal lung tissues, presumed to induce an immune tolerance to tumor neoantigens, was associated with a shorter DFS after curative-intent surgery." (PMID 36108261, 2022). "More importantly, PD-1+ICOS+ CD4 Th cells were enriched in T cells recognizing tumor-associated antigens such as HPV but also tumor specific neoantigens." (PMID 35937775, 2022). "Upregulation or activation of Tregs is associated with higher ICOS expression in tumor-infiltrating T cells." (PMID 36276141, 2022). "Further, the expression level of immune checkpoint molecules (PDL1, CTLA4, LAG3, TIGIT, CD27, IDO1, ICOS) and tumor mutational burden (TMB) also showed significant differences between the two subtypes, indicating the clinical value of the two subtypes." (PMID 36568197, 2022). "The tumor‐associated double‐positive T (DPT) cells are found enriched in L regions with expression of PD‐1/HLA‐DR/ICOS/CD45RO." (PMID 32670760, 2020). "The tumor‐associated CD4/CD8 double‐positive T (DPT) cells are found enriched in L regions with synergetic expression of PD‐1/HLA‐DR/ICOS/CD45RO and exhibit a higher level of IFN‐γ, TNF‐α, and PD‐1 upon stimulation." (PMID 32670760, 2020). "This is indirect evidence that modulation of the ICOS pathway on peripheral pDC negatively affects tumor-associated immunity." (PMID 30788290, 2019). "Our findings suggest that ICOS-expressing immune cells include tumour neoantigen-specific T-cells and are associated with favourable prognosis, at least in ESCC." (PMID 31882943, 2019). "Tumor associated pDC found in close proximity to ICOS+ Treg in breast cancer, liver cancer, and ovarian cancer are associated with poorer survival." (PMID 30788290, 2019). "Example biomarkers of interest currently includes cell surface molecules such as PDL1, CD70 and ICOS expression, tumour mutational load by exome sequencing, as well as detailed immune cells analysis by immune profiling or by TCR sequencing." (PMID 27777776, 2016). "This response was associated with an increase in ICOS+ CD8 T cells and tumor-specific CTL activity in tumor draining lymph nodes along with an increase in ICOS+ CD8 T cells in responding tumours." (PMID 25518732, 2014). "This correlation, in turn, is associated with the expression of ICOS on tumor infiltrating Tregs." (PMID 38927922, 2024).
tumor (continued). "Additionally, Carapeto reported that ICOS expression is greater at the tumor margin compared to the tumor center, and low ICOS expression in iCCA is associated with poor OS." (PMID 39845973, 2024). "Tregs might promote CRC progression by suppressing ICOS expression, inducing polarization of tumor-associated macrophages to the M2 type." (PMID 39104717, 2024). "High levels of Tregs might induce tumor-associated macrophages to polarize towards the M2 type by inhibiting ICOS expression." (PMID 39104717, 2024). "Second, although we found that ICOS expression is associated with tumor immune cell infiltration and patient survival, it may affect the survival of patients through immune infiltration cells." (PMID 36855091, 2023). "Finally, PD-1+ICOS+CD4+ Th TILs were demonstrated to recognize both tumor-associated antigens and tumor-specific neoantigens." (PMID 36451828, 2022). "Finally, these PD-1+ICOS+ CD4+ Th TILs were shown to recognize both tumor-associated antigens and tumor-specific neoantigens." (PMID 35439168, 2022). "The ICOS pathway may have a more prominent role in anti-tumor activity than immunosuppression as ICOS/ICOSL-deficient mice show impaired anti-tumor activity in response to anti-CTLA-4." (PMID 35326731, 2022). "Interestingly, different studies showed correlation between ICOS rs4404254 or rs4675379 and ICOS expression in different tumours, where ICOS rs4404254(C) allele and rs4675379(C) are associated with tumour risk." (PMID 35664973, 2021). "Interestingly, expression data from immune ROIs indicated that the presence of EpCAM and cytokeratin was associated with better patient OS, while the presence of CD34, CD3, and ICOS in tumour ROIs was associated with better patient OS." (PMID 33261133, 2020). "Univariate Cox proportional hazards indicated that the presence of cells expressing CD3 (hazard ratio (HR): 0.5, p = 0.018), CD34 (HR: 0.53, p = 0.004), and ICOS (HR: 0.6, p = 0.047) in tumour compartments were significantly associated with improved overall survival (OS)." (PMID 33261133, 2020). "In addition, the expression of ICOSL in malignant tumor cells or tumor-associated pDCs was confirmed to be a good booster for the accumulation of ICOS+ Tregs in some tumor tissues." (PMID 32983168, 2020). "Univariate Cox proportional hazard analysis indicated that the presence of cells expressing CD3 (hazard ratio (HR): 0.5, p = 0.018), CD34 (HR: 0.53, p = 0.004), and ICOS (HR: 0.6, p = 0.047) in tumour compartments was associated with improved overall survival (OS)." (PMID 33261133, 2020). "Finally, the Tregs in the periphery compromised 9.59 ± 4.30% of the CD4+ T-cells, were characterised by high levels of TIGIT and ICOS expression albeit at lower levels compared to their tumour-associated counterparts (~30% higher median expression, respectively)." (PMID 33917832, 2021). "However, in addition to targeting co-inhibitory pathways to remove tumor-associated immune suppression, there is strong interest in targeting co-stimulatory molecules such as ICOS in an attempt to prolong T cell responses and promote desirable effects such as immunological memory." (PMID 30788290, 2019). "Our flow cytometric analysis showed differential expression of IL7R, CD40L, PD1, ICOS and HLA-DR between tumor Tfh-like subsets defined based on CD49f and CD103 expression within the CD4+ gate." (PMID 41542042, 2026). "On the contrary the subgroup high in ICOS, the main ICOSLG receptor, harbored NOTCH pathway mutations, showed an inflamed tumor microenvironment, better prognosis, and prolonged OS with chemo-immunotherapy (HR = 0.52, p = 0.003)." (PMID 42253933, 2026). "The interaction between ICOSLG and its receptor, ICOS, promotes the development of T regulatory cells in healthy bone marrow as well as in different tumor microenvironments." (PMID 41596324, 2026).
tumor (continued). "We observed that the numbers of Tbet+ICOS+ Th1-like CD4+ T cells in tumors correlated to reduced frequencies of CD45−CD31high tumor endothelial cells and increased frequencies of MECA-79+ TA-HECs after anti-CTLA-4 treatment." (PMID 40460830, 2025). "In the complete tissue dataset (GSE138709), visualization of the ICOS signaling network revealed striking differences between adjacent and tumor tissues." (PMID 41180156, 2025). "The authors observed that CD4+ T cells from both blood and tumour tissue of all treated patients expressed increased levels of ICOS and produced IFN-γ." (PMID 39325360, 2025). "FX1 administration reduced the expression of Foxp3, CD25, GITR, and ICOS in Treg cells from the dLNs, but had little impact on the expression of these molecules in tumor-infiltrating Treg cells." (PMID 40290124, 2025). "Three markers (CD10, PD1, and ICOS) were positive in the current case; thus, the tumor cells were identified as TFH cells." (PMID 41404220, 2025). "Our analysis revealed that HPV-positive tumors harbored more mature, tumor-proximal TLSs enriched with ICOS+ CD4+T- cells and CD45RO+T- cells, as well as CD21+ B- cells, supporting the presence of mature TLSs and active immune priming." (PMID 41254766, 2025). "Our data suggest an important contribution of Tbet+ICOS+ Th1-like CD4+ T cells in the remodeling of tumor blood vessels and the increase of TA-HEVs during treatment with anti-CTLA-4 antibodies." (PMID 40460830, 2025). "The critical role of ICOS signaling in maintaining T cell function and survival within the immunosuppressive tumor microenvironment has positioned it as a promising target for next-generation CAR-T cell design." (PMID 40519924, 2025). "Functional validation experiments confirmed the crucial role of ICOSL in mediating DC–T cell interactions under tumor-conditioned conditions, highlighting the potential of targeting the ICOS–ICOSL axis as a therapeutic strategy in CCA." (PMID 41180156, 2025). "ICOS, as a T cell co‐stimulatory molecule, induces the accumulation of mitochondrial reactive oxygen species (ROS) in tumor cells by promoting the secretion of pro‐inflammatory factors (such as TNF‐α), indirectly activating MPT‐related pathways." (PMID 40747615, 2025). "First, we treated APP mice with a neutralizing antibody against IL-33, which eventually reduced the tumor size and number of proliferating cells and ICOS-positive ILC2s within the tumors." (PMID 40761291, 2025). "Flow cytometry analysis further revealed that combined therapy significantly increased the frequency of MECA-79+ TA-HECs and MECA-79+CD62P+ TA-HECs and tumor infiltration of Tbet+ICOS+ Th1-like CD4+ T cells and CD8+ T cells." (PMID 40460830, 2025). "They noted worse survival in patients with high PD-L1 and LAG-3 expression along with low CD3, CD4, and ICOS expression, especially in the tumor center." (PMID 39751894, 2025). "There was a higher expression of ICOS in tumor-infiltrating lymphocytes, especially regulatory T cells in cancer." (PMID 40040723, 2025). "Tumor-infiltrating Tregs expressed high levels of cell surface molecules associated with T-cell activation, such as CTLA4, PD-1, LAG3, TIGIT, ICOS, and TNF receptor superfamily members." (PMID 40092987, 2025). "Costimulatory molecules, such as CD28, 4-1BB, and ICOS, are essential for activating tumor-specific T cells, leading to their proliferation and activation for effective tumor clearance." (PMID 40260303, 2025). "When genetically fused to pembrolizumab, Y8 further enhanced T-cell activation and tumor cell lysis, demonstrating synthetic synergy between PD-1 blockade and ICOS agonism." (PMID 40646580, 2025). "T cells within tumor-enriched neighborhoods presented increased expression of effector and exhaustion markers such as PD-1, Granzyme B, and ICOS, whereas those in stromal-enriched neighborhoods presented reduced activation marker expression." (PMID 41254766, 2025).
tumor (continued). "The authors demonstrated that CD4+ ICOS+ T cells constitute a subset of effector Th1 cells specific to tumour antigens." (PMID 39325360, 2025). "In HPV-positive tumors, PD-L1+ tumor cells were enriched at the tumor-immune interface, and ICOS+ CD4 T- cells were enriched in the tumor core, suggesting enhanced tumor-reactive T-cell activity." (PMID 41254766, 2025). "CD275, also known as inducible costimulator ligand (ICOS-L), is expressed by DCs, macrophages, and tumor cells, and interacts with its receptor ICOS on T cells, thereby playing a crucial role in modulating immune responses within the TME." (PMID 40724825, 2025). "Studies on head and neck squamous cell carcinoma and colorectal cancer tumor tissues have revealed that the co-expression of PD-1 and ICOS on solid tumors identifies CD4+ T cells reactive to the tumor." (PMID 38426090, 2024). "Inducible T-cell co-stimulator (ICOS) is a co-stimulatory receptor highly expressed in tumor-infiltrating lymphocytes in many cancer types." (PMID 38349570, 2024). "Tregs, known for their highly suppressive and hyperproliferative features in the TME, express heightened levels of CD25, CTLA4, GITR, OX40, ICOS, and neuropilin-1 and accumulate significantly during tumor development." (PMID 38787791, 2024). "In tumor cells, high-level ICOSL expression activated by ICOS significantly reduces tumor cell metastasis, indicating that the inhibitory effect of ICOS-mediated ICOSL triggering surpasses the promoting effect of OPN-mediated ICOSL triggering." (PMID 39104717, 2024). "The expression levels of M2 macrophages and Tregs were significantly positively correlated with tumor markers, while ICOS expression was significantly negatively correlated." (PMID 39104717, 2024). "We found an increased expression of the costimulatory receptor ICOS in peripheral CD56dim and CD56bright NK cells in CC patients, as well as a 3-fold increase in expression in tumor-infiltrating NK cells." (PMID 39201462, 2024). "ICOS expression has been demonstrated to be expressed at intermediate levels in immune-active tumour-infiltrating Th1 cells." (PMID 38440738, 2024). "An exhausted population is also highly increased in tumor-infiltrating NK cells, and it shows a dramatically increased expression of the costimulatory receptors ICOS (>15×) and 4-1BB (>10×) compared to peripheral NK cells." (PMID 39201462, 2024). "butyrate restrains anti-CTLA-4-induced up-regulation of CD80/CD86 on dendritic cells and ICOS on T cells, accumulation of tumor-specific T cells and memory T cells." (PMID 39351241, 2024). "ICOS, a T-cell immune-costimulatory receptor, regulates tumour immunity via two different mechanisms." (PMID 38556542, 2024). "ECT combined with ICOS activation led to increased infiltration of immune cells, decreased tumor volume, and improved overall survival." (PMID 39451782, 2024). "Both HCC- and CCA-derived tumour infiltrating Tregs express high levels of co-stimulatory IgSF (ICOS) and TNFRSF (4-1BB, OX40, GITR) members." (PMID 38440738, 2024). "ICOS not only promotes the activation of anti‐tumor cytotoxic T cells, but also promote the immunosuppressive activity of Treg to play a pro‐tumor character." (PMID 38506253, 2024). "For example, possible differentiation derived from single‐positive T‐cell tumour‐associated CD4/CD8 double‐positive T (DPT) cells recently identified at the tumour border exhibit synergistic expression of PD‐1, HLA‐DR, ICOS, and CD45RO." (PMID 39350478, 2024). "Multiplex immunofluorescence showed that PD-1- and ICOS-expressing T cells were in close proximity to the tumor cells." (PMID 39312285, 2024). "The expression levels of M2 macrophages and Tregs increased with tumor progression, while ICOS expression showed a decreasing trend." (PMID 39104717, 2024). "This inquiry remains crucial since ICOS mRNA overexpression in tumor biopsies compared to normal tissues has been detected in more than 30 types of cancers." (PMID 39201462, 2024).
tumor (continued). "Our study demonstrates for the first time the increased expression of the costimulatory receptors ICOS, 4-1BB, and OX-40 in peripheral CD56dim, CD56bright, and tumor-infiltrating NK cells in CC." (PMID 39201462, 2024). "ICOS, which is a hallmark of CD8+ tissue-resident memory T cells, had higher expression in TC,57− in tumor-sparse regions." (PMID 39001353, 2024). "The expression levels of M2 macrophages and Tregs increase with tumor progression, whereas ICOS expression decreases." (PMID 39104717, 2024). "For example, the OPN-mediated activation of ICOSL promotes the migration of various tumor cell types and enhances tumor angiogenesis, while the ICOS-mediated activation inhibits these processes." (PMID 39596455, 2024). "One of them suggests that tumor cells express ICOS (inducible T-cell costimulator) ligand and CD80/CD86 on their surface in amounts sufficient for co-signaling of the CTL through the CD28 costimulatory family." (PMID 38672662, 2024). "An increased expression of ICOS indicates that T cells are involved in antigen recognition, but the function can be dual with either anti-tumor or tumor promotion responses." (PMID 39001353, 2024). "The expression of ICOS and PD-L1 proteins on the tumor cells of patients with NSCLC was regionally distributed in most cases." (PMID 38616999, 2024). "Consistent with these expression patterns, in preclinical studies, ICOS signaling either promoted pro-tumour responses (via Tregs) or anti-tumour responses (via Th1, Tfh, or CTL)." (PMID 38440738, 2024). "In T cells, immune stimulation by the tumor led to the up-regulation of many co-stimulatory receptors, including ICOS, TNFRSF18, TNFRSF4, and TNFRSF9/4-1BB." (PMID 39475596, 2024). "Dianzani C and others found that ICOS-Fc treatment inhibited tumor cell migration to the lungs in mice, increasing IL-17A and RAR-related orphan receptor C (RORc) expression while reducing IL-10 and Foxp3 expression." (PMID 39104717, 2024). "ICOS was shown to be involved in the regulation of the tumor immunity through two different perspectives." (PMID 38127899, 2023). "Alongside changes in target expression, significant increases in serum IFNγ levels and T-cell activation/function in tumor-draining lymph nodes were observed following treatment with the mIgG1 anti-ICOS mAb and the anti-PD-1 mAb combined." (PMID 37593752, 2023). "ICOS/ICOSL expressed in regulatory T‐cells (Tregs) within the tumor microenvironment largely influences T‐cell‐mediated tumor immune tolerance." (PMID 37850501, 2023). "As we currently know, ICOS is positive regulator of T-cell function in anti-tumor immune response, but also involving the function of immune escape as its association with suppressive Tregs." (PMID 38127899, 2023). "CD8 with ICOS and PD-L1 positive cells were more abundant in the sclerotic tumor (p = 0.0309 and p = 0.0112 respectively)." (PMID 36980192, 2023). "In vitro experiments have demonstrated that ICOSL, stimulated by a soluble recombinant form of ICOS (ICOS-Fc), effectively prevents the adhesion and migration of DCs, ECs, and tumor cells." (PMID 37666809, 2023). "High expression of ICOS showed significance in terms of both PFS (p = 0.040) and OS (p = 0.041) while high PD-L1 expression in tumour was associated with better OS (p = 0.033)." (PMID 37527282, 2023). "Feladilimab (mAbID 1010), a humanized IgG4-kappa mAb, acts as an agonist of ICOS, activating Teff cells, which mediate a cytotoxic anti-tumor immune response." (PMID 37215135, 2023). "Further CD8 T cells with co-expression of ICOS were significantly more present in the sclerotic tumor." (PMID 36980192, 2023). "Another study, using TCGA and tumor‐infiltrating immune cells, analyzed the expression profile of multiple co‐stimulatory and inhibitory cells, including ICOS." (PMID 37850501, 2023).